BRAF (B-Raf proto-oncogene, serine/threonine kinase)
Diseases named in the same sentence as BRAF in open-access papers (continued):
Sharing a sentence is not in itself a finding about the gene and the disease.
melanoma (continued). "It is essential to identify biomarkers and develop risk models for predicting the immune microenvironment, prognosis, and immunotherapy response in BRAF V600E-mutant and WT melanoma." (PMID 36704723, 2023). "Wild-type RAF isoforms function as homo- and heterodimers, and BRAF/CRAF heterodimers drive ERK signaling downstream of mutant NRAS in MEKi-sensitive melanoma cells." (PMID 36765910, 2023). "A PLK inhibitor showed synergy with only one of two BRAF (upstream of MEK) inhibitors studied in a panel of melanoma cell lines, and demonstrated efficacy in a NRAS mutant melanoma." (PMID 37126527, 2023). "The combination of vemurafenib, cobimetinib, and atezolizumab has recently been approved by the FDA for the treatment of BRAF-mutant melanoma, which was shown in a phase III clinical trial to improve progression-free survival." (PMID 37581538, 2023). "We demonstrated that peripheral blood PD-L1+ PMN frequency predicts patient prognosis and response to the anti-PD-1 agent nivolumab in patients with stage IV BRAF wild-type melanoma." (PMID 37525065, 2023). "Among them, genetic alterations leading to abnormal activations of the Ras signaling pathway represent the most common oncogenic driver mutations, particularly BRAF and NRAS mutations, which occur in approximately 50% and 15% of melanomas, respectively." (PMID 37404751, 2023). "Constitutive ERK signaling was shown to downregulate IFNAR1 expression in BRAF mutant melanomas, which made the tumors resistant to type I interferon-mediated growth inhibition." (PMID 37803324, 2023). "Activated CAFs can trigger melanoma progression and resistance to BRAF/MEK inhibitors via the release of soluble molecules including neuregulin 1 and hepatocyte growth factor (HGF) as well as fibronectin." (PMID 37370757, 2023). "Chronic PLX4032 treated G361 and SKMEL5, however, yielded resistant cells with elevated PPARGC1A expression, which parallels the other end of the change-in-expression continuum seen across melanoma biopsies pre-/post-BRAF inhibitor treatment." (PMID 37277330, 2023). "As in melanoma, the combination of dabrafenib and trametinib (BRAF and MEK inhibitors) acts in a synergistic manner against BRAF mutations and the underlying metabolic pathways." (PMID 36836402, 2023). "BRAF-mutated (BRAFV600E/K) melanomas account for 40% of cutaneous melanomas, and the presence of the BRAFV600E/K is specifically predictive of response to the approved BRAF inhibitors." (PMID 37295047, 2023). "BRAF analysis of the primary melanoma by real-time PCR (rtPCR) using the EasyPGX Ready BRAF system (Diatech Pharmacogenetics), specific only for BRAF V600 variants, did not detect any mutations." (PMID 37569660, 2023). "Recently, in BRAFV600 mutant melanoma, a subpopulation of persister cells was discovered to survive through reversible remodeling of mRNA translation after treatment with BRAF and MEK inhibitors." (PMID 37638338, 2023). "It was previously shown that the selective pan-RAF inhibitor TAK-632 exhibits synergistic effects with the MEK inhibitor TAK-733 in BRAF inhibitor-resistant melanoma." (PMID 38111008, 2023). "Combinatorial treatment with BRAF and MEK inhibitors constitutes an effective therapy against melanomas harboring BRAF V600-missense mutations." (PMID 37277330, 2023). "EGFR expression is repressed by gene methylation in melanomas, which confers sensitivity to BRAF inhibitors alone." (PMID 37422534, 2023). "This is significant given that melanoma was one of the first systemic malignancies to demonstrate the cerebral penetrance of systemic therapy and role of molecular drivers (BRAF) in prognostication." (PMID 37835467, 2023). "Overcoming resistance to BRAF inhibitors in melanoma is a complex challenge, but researchers have been investigating various strategies to address this issue." (PMID 37504268, 2023).
melanoma (continued). "In line with this concept, we have previously shown that SREBP-1-mediated lipogenesis plays a critical role in maintaining therapy resistance in BRAF mutant melanoma and that SREBP-1 inhibition elevates lipid peroxidation, exerting a cytostatic effect." (PMID 37072838, 2023). "Using an in vivo assay in A375-X1-resistant melanoma cell-transplanted mice, they first proved that treatment with combined BRAF and ALK inhibitors can stop tumor growth." (PMID 36831417, 2023). "Targeted anti-BRAF and anti-MEK therapy have also been shown to be effective for cytoreduction in BRAF-mutated melanoma." (PMID 37444454, 2023). "Patient 1 - A 37-yr-old man with a superficial spreading BRAF-positive melanoma was found to harbour a progressively growing left adrenal mass." (PMID 36604647, 2023). "Patients with BRAF subtype melanomas have been reported to be younger on average as compared to patient with other subtypes." (PMID 36865793, 2023). "Currently, BRAF-V600E inhibitors such as Zelboraf and Dabrafenib are approved for the treatment of melanoma, while their use in ameloblastoma is still under investigation." (PMID 37646022, 2023). "Our results show some parallels to efforts to establish combinations for BRAF-mutated colorectal cancer tumors, which are less sensitive to BRAF inhibitor monotherapy than are melanomas." (PMID 36752207, 2023). "For instance, CRISPRa screening in a V600E melanoma cell line treated with BRAF inhibitors revealed previously-known as well as novel gene components that confer resistance to the inhibitor." (PMID 37908590, 2023). "Similar dose-limiting toxicities emerged in BRAFV600-mutant advanced melanoma patients treated with the combination of buparlisib and the BRAF inhibitor vemurafenib." (PMID 36765661, 2023). "Despite an initial response of most melanomas, complete long-term responses are uncommon and patients frequently develop acquired resistance to anti-BRAF monotherapy." (PMID 36765875, 2023). "Several mutations, known as driver mutations (BRAF, NRAS, KIT, GNAQ, GNA11, NF1, and TERT), define most of the molecular subtypes of melanoma." (PMID 37583899, 2023). "Somatic NF1 mutations often co-occur with other genetic alterations, particularly BRAF and NRAS mutations, which are common in melanoma." (PMID 37504268, 2023). "In melanoma, a combination of the BRAF inhibitor dabrafenib and mitogen-activated protein kinase kinase (MEK) inhibitor trametinib showed superior efficacy over dabrafenib alone." (PMID 37422534, 2023). "Inhibition of CDK2 in melanoma cell lines has been shown to overcome their resistance to BRAF and Hsp90 inhibitors, while BUB1 has been identified as a novel target downstream of SIRT1 in melanoma." (PMID 38023136, 2023). "Two randomized studies, SECOMBIT and DREAMseq, investigated the optimal first-line treatment in patients with BRAF-mutant unresectable melanoma." (PMID 37543586, 2023). "In BRAF-mutant melanoma, the dynamics of ERK signaling and DTP formation are directly influenced by the kinetics of receptor tyrosine kinase activation." (PMID 37917191, 2023). "BRAF is a potent oncogene, present in approximately 50% of all melanomas in the White population, that plays a critical role in the Ras-Raf-mitogen-activated protein kinase/extracellular signal-related kinase (MEK) cell-signaling pathway." (PMID 36998456, 2023). "Here, we perform a high-throughput chemogenetic drug screen in GNAQ-mutant UM contrasted with BRAF-mutant cutaneous melanoma, defining the druggable landscape of these distinct melanoma subtypes." (PMID 37858338, 2023). "In contrast, resistance to the BRAF inhibitor vemurafenib recurrently selected for a gain of chr7 in the BRAF mutant colorectal cancer cell line Colo205, but for recurrent gains of chr11 and 18 in A375, a BRAF mutant melanoma cell line." (PMID 37640903, 2023).
melanoma (continued). "Like studies in melanoma, where BRAF inhibitor monotherapy shows rapid but transient MAPK pathway inhibition, PLX4720 treatment in glioma cell lines (M-38, DBTRG-05MG and NMC-G1) did not suppress MAPK pathway signaling in a durable way." (PMID 37920169, 2023). "We further show that while AKT2 is dispensable for melanoma initiation, AKT1 contributes to BRAF-driven murine melanoma initiation and cell proliferation, which is in line with our previous results." (PMID 37894325, 2023). "In this systematic review and meta-analysis of seven studies, including 400 patients, we assessed the efficacy and safety of rechallenging BRAF-mutant advanced melanoma patients with BRAFi/MEKi." (PMID 37568570, 2023). "V600E-containing BRAF has been an effective target in melanoma treatment, and the patient was subsequently treated with vemurafenib (a BRAF inhibitor) at 720 mg orally twice daily." (PMID 37627272, 2023). "Inhibition of MT1-MMP by shRNA in resistant melanoma cells was able to restore their sensitivity to BRAF-targeted therapies." (PMID 37174072, 2023). "Although BRAF mutant inhibition has proven effective in treating melanoma, its efficacy in NSCLC is limited due to the development of resistance." (PMID 37444584, 2023). "Compared with more common BRAF-mutant melanomas (50–70% of cases), the understudied NRAS-mutant subtype (15–25% of cases) is more aggressive, and patients have a lower median overall survival." (PMID 36765910, 2023). "In particular, standard treatments include BRAF inhibitors for melanoma, osimertinib for NSCLC, hormone therapy or HER2 TT for breast cancer, and imatinib for GIST." (PMID 37888038, 2023). "The dual inhibition of BRAF and MEK had become the standard of care for BRAF V600 mutant melanoma in 201514." (PMID 36967525, 2023). "In melanoma, after the exposure to BRAF-inhibitors, two different pathways can be reactivated, resulting in the development of resistance: the MAPK and the PI3K/AKT/AKT pathways." (PMID 36831417, 2023). "In melanoma with CDKN2A germline mutations, there are usually somatic mutations in BRAF and NRAS genes, NRAS mutations being the most common ones." (PMID 36805510, 2023). "Several miRNAs have been detected in body fluids, such as serum and plasma, which are able to monitor the therapeutic response to BRAFi and MEKi treatment in BRAF-mutant melanoma patients." (PMID 37627054, 2023). "The most common are activating mutations in the BRAF gene (especially BRAF V600E, followed by BRAF V600K), which are found in 50% of patients and are more common in superficial spreading melanoma." (PMID 37504268, 2023). "The relative ratio of the circulating levels of miR-4888/miR-579-3p allowed us to predict response to BRAFi/MEKi treatment in BRAF-mutant melanoma patients." (PMID 37627054, 2023). "In the context of melanoma, HO-1 has been reported to promote cell proliferation through the BRAF-MAPK signaling pathway." (PMID 37507910, 2023). "Cancers effectively treated by BRAF inhibition, such as most melanomas, probably belong to the first category, while other cancers refractory to BRAF-targeted treatment likely belong to the second category." (PMID 38136350, 2023). "NRAS and BRAF mutations are almost always mutually exclusive, where NRAS mutations occur in about 20% of melanoma cases." (PMID 37762707, 2023). "He had a background of long standing inactive Crohn's disease on ustekinumab (an interleukin[IL]-12 and IL-23 inhibitor), and more recently, stage IV melanoma (BRAF wild-type) with known symptomatic vertebral metastases." (PMID 36895912, 2023). "For the present study, we have chosen two BRAFV600 melanoma cell lines that differed in the activity of the BRAF/MEK/ERK pathway after they developed resistance to trametinib (TRA), 29_TRAR (p-MEK1/2low/p-ERK1/2low) and 21_TRAR (p-MEK1/2high/p-ERK1/2high)." (PMID 37835493, 2023).
melanoma (continued). "Another clinical trial confirmed the significant benefit of nivolumab (monoclonal antibodies targeting PD-1) for advanced BRAF wild-type melanoma." (PMID 37205993, 2023). "We explored BRAF-related biological features in melanoma and established a prognostic signature taking into consideration the clinical risk factors to precisely predict the probability of OS for melanoma patients." (PMID 37205993, 2023). "Success of the following COMBI‐AD trial contributed to the only approval of adjuvant targeted therapy with Dabrafenib plus Trametinib combination for Stage III BRAF‐mutant melanoma." (PMID 37016119, 2023). "Previously, we found that ABL kinases are activated by receptor tyrosine kinases such as EGFR, PDGFR, and IGF1R, and BRAF contributes to ABL1/2 activation in melanoma cells harboring BRAF-V600E." (PMID 36765910, 2023). "Specifically, we analyzed RNAseq data from patient biopsies of BRAF-mutant melanoma before treatment with the BRAF inhibitor vemurafenib and after the development of acquired resistance." (PMID 37226094, 2023). "We investigated the performance of several tissue classifiers, with two types of cross-validation in order to identify proteomic differences characterizing BRAF and NRAS mutated melanoma." (PMID 36982192, 2023). "In this way, pharmacological inhibition of AURKA by MLN8237 (alisertib) resulted in the reduction of melanoma cell proliferation and induced senescence and apoptosis in cells with BRAF and NRAS mutation, and in vemurafenib (BRAF inhibitor) resistant cells." (PMID 37259298, 2023). "Many studies have verified that the addition of a MEK inhibitor to a BRAF inhibitor improved progression-free survival and overall survival over BRAF inhibitor monotherapy in patients with BRAFV600E-mutant melanoma." (PMID 36624452, 2023). "For example, melanoma patients harboring BRAF V600E were found to respond well to vemurafenib, while those with colorectal cancer did not." (PMID 36910668, 2023). "In vitro, BRAF inhibitor (BRAFi)-resistant melanoma cells characterized by dedifferentiated mesenchymal-like or NCSC-like phenotypes display a pronounced mechanosensitivity and elevated mechanosignaling when plated on rigid collagen substrates." (PMID 36774337, 2023). "Initially, kinase inhibitors (KI) such as BRAF V600E-targeting vemurafenib and dabrafenib (both second generation) showed promising results in melanoma, and even more so when combined with IR." (PMID 36229655, 2023). "This group has reported that targeting DDR1 and DDR2 was able to overcome collagen matrix-mediated tumor cell resistance to BRAF-targeted therapy in melanoma." (PMID 37174072, 2023). "Altogether these findings underscore not only a potential oncosuppressive role for nestin in BRAF-mutant melanomas but also unveil its potential as a predictive marker of clinical response to targeted therapy." (PMID 38008717, 2023). "On the other hand, BRAF and NRAS mutations are frequently encountered in dedifferentiated melanomas with conventional nodular or superficial spreading components." (PMID 37373134, 2023). "Given the vital implications of BRAF mutations in melanoma, GSEA was performed to analyze DEGs between the BRAF mutant and wild-type groups." (PMID 37205993, 2023). "Of these, combined inhibition of BRAF and MEK is, in addition, clinically used for treatment of BRAF V600-mutated NSCLC and melanoma." (PMID 40809499, 2023). "Current data advices for immunotherapy based regiments in patients with BRAF mutant melanoma or, possibly, sandwich approach." (PMID 37543586, 2023). "Currently, anti-PD-1 or BRAF-directed adjuvant treatments are indicated in melanoma patients with stage IIIA (with sentinel lymph node metastasis >1 mm), IIIB, IIIC, and IIID." (PMID 37888038, 2023). "Functionally, TCF12 enhances melanoma proliferation and metastasis, as well as the sensitivity to BRAF(V600E)-targeted therapy." (PMID 37760480, 2023).
melanoma (continued). "With different drug approval deadlines in China, anti‐PD1 monotherapy, D + T combination, and Vemurafenib (V) monotherapy have all been used in real clinical practice as adjuvant settings for stage III BRAF‐mut melanoma in recent years." (PMID 37016119, 2023). "Taking BRAF-mutant melanoma as paradigm, we demonstrate that FASN expression is consistently increased upon onset of therapy resistance and is associated with decreased lipid poly-unsaturation." (PMID 37072838, 2023). "The most common mutations in melanoma involve the MAPK signaling pathway, where acquired mutations in the genes encoding two kinases, BRAF and NRAS, result in continuous activation and aberrant cell proliferation." (PMID 37762707, 2023). "In one study, a ketogenic diet was shown to affect BRAF V600E mutation-dependent MEK1 activation in a xenograft mouse model, contributing to increased human melanoma growth in this model." (PMID 37836444, 2023). "In this respect, exosomes containing BRAF siRNA were shown to have increased anti-tumoral activity compared to siBRAF in melanoma cell lines." (PMID 37958863, 2023). "Melanoma is the most lethal type of skin cancer and is an archetypal malignancy for the development of both targeted therapy (with BRAF and MEK inhibitors) and especially immunotherapy." (PMID 36949413, 2023). "In this sense, similar results in regard to a synergic effect between LDL-signaling and BRAF V600E were described in melanoma, colorectal and lung cancer cells." (PMID 37446330, 2023). "The trial explored both the safety and efficacy of vemurafenib administered to 122 non-melanoma patients, including 22 NSCLC patients, with the V600 BRAF mutation." (PMID 37111737, 2023). "The molecular classification of melanomas has practical consequences since the BRAF and KIT mutant forms can be treated by targeted therapies." (PMID 36980598, 2023). "This combination therapy currently represents the approach taken in melanoma to combat resistance, and the concept is currently being investigated in a phase II clinical trial combining dabrafenib and trametinib in BRAF V600–mutant pLGG." (PMID 37124503, 2023). "The population was characterized by BRAF-mutant advanced melanoma patients, who had targeted therapy in the first or second line of treatment, with either the combination of BRAFi/MEKi or BRAFi alone." (PMID 37568570, 2023). "BRAF V600E melanoma cells have been found to produce key cytokines involved in inflammation such as IL-1β, IL-6, IL-8, and TGF-β as signals, for instance, for neutrophil recruitment." (PMID 37627054, 2023). "This is in line with previously reported WES data which showed acquisition of resistance to BRAF inhibitors due to BRAF gene amplification in around 20% of melanoma patients." (PMID 36901733, 2023). "To date, MAPK-directed therapies have been successful in certain indications (i.e., BRAF V600E melanoma), encouraging in some (BRAF V600E colorectal cancer, KRAS G12C NSCLC), but have achieved only modest results in others." (PMID 37507765, 2023). "Therapeutically, upregulation of adipocyte enhancer-binding protein 1 (also upregulated in WM-266-4-derived exosomes) has also been shown to contribute to resistance to BRAF (V600E) inhibition in the treatment of melanoma." (PMID 36831440, 2023). "Although absolute recommendations on medical practice are hard to establish from our current review, it is likely to infer that anti‐PD‐1 inhibitors and a combination of BRAF/MEK inhibitors are hopeful candidates for wide use in melanoma treatment." (PMID 36030506, 2023). "In conclusion, comorbidities and geographical region determine the choice of adjuvant treatment in patients with resected stage III BRAF-mutant melanoma." (PMID 36672358, 2023).